Y_RNA (Y RNA )
Gene: Miscellaneous RNA gene on chromosome 3 (122,025,195 to 122,025,304, reverse strand). Ensembl gene ENSG00000202388.
Homologues: Orthologues: chimpanzee Y_RNA (71% identical), macaque Y_RNA (61% identical). Paralogues in human: RNY1 (77% identical), Y_RNA (75% identical), Y_RNA (74% identical), Y_RNA (73% identical), RNY1P8 (72% identical), Y_RNA (72% identical), RNY1P11 (71% identical), Y_RNA (71% identical), RNY1P3 (70% identical), RNY1P7 (70% identical), Y_RNA (70% identical), RNY1P5 (69% identical), and 86 more.